DCN (decorin)
Diseases named in the same sentence as DCN in open-access papers (continued):
Sharing a sentence is not in itself a finding about the gene and the disease.
oral squamous cell carcinoma (4 papers, 2012 to 2025). "Low DCN expression levels, along with increased biglycan expression, has been shown to correlate with a poorer outcome for oral squamous cell carcinoma patients." (PMID 37760543, 2023). "Since nuclear decorin silencing resulted in down regulation of a variety of proangiogenic mediators, we examined whether decorin silencing has any effect on angiogenesis of oral squamous cell carcinoma." (PMID 22507529, 2012).
systemic sclerosis (4 papers, 2004 to 2022). A chronic disorder, possibly autoimmune, marked by excessive production of collagen which results in hardening and thickening of body tissues. "Decorin contributes to the collagen fibril stability and high levels of decorin seem to be closely linked to dermal fibrotic stages as known from systemic sclerosis." (PMID 15385052, 2004). "They demonstrated that decorin was overexpressed in patients with NSF compared to patients with systemic sclerosis (P value < 0.014), hemodialysis patients (P value < 0.0074), and healthy controls (P value < 0.0001)." (PMID 23193473, 2012). "Similar to DCN, decreased BGN expression was also found in fibroblasts isolated from the skin of systemic sclerosis patients." (PMID 32063855, 2019). "They assessed mRNA expression of decorin, versican and TGF-β in skin specimens of 10 patients with NSF, 16 patients with systemic sclerosis, 8 patients without NSF on hemodialysis and 17 healthy controls." (PMID 23193473, 2012).
triple-negative breast carcinoma (4 papers, 2017 to 2024). An invasive breast carcinoma which is negative for expression of estrogen receptor (ER), progesterone receptor (PR), and human epidermal growth factor receptor 2 (HER2). "Indeed, we have shown that the triple-negative breast cancer cells MDA-MB-231 reduced the level of DCN and increased the level of α-SMA and FAP-α in normal breast fibroblasts in a paracrine manner." (PMID 38667295, 2024). "As decorin induces rapid Thrombospondin 1 (TSP-1) secretion in triple negative breast carcinoma cells, we hypothesized that the decorin-inducible Peg3 could be directly involved in stimulating the release and potential synthesis of TSP-1." (PMID 28174297, 2017). "Although decorin is regarded as the “endogenous guardian” and biglycan acts as a danger signal in cancer, asporin acts as an oncogene in some types of cancer (breast, pancreatic, colorectal, gastric, and prostate), but as a tumor suppressor gene in triple-negative breast cancer." (PMID 31608236, 2019).
Alzheimer disease (3 papers, 2013 to 2023). A progressive, neurodegenerative disease characterized by loss of function and death of nerve cells in several areas of the brain leading to loss of cognitive function such as memory and language. "Moreover, in mouse models, increased decorin levels in cerebrospinal fluid (CSF) have been shown to be associated with early formation of Aβ amyloidosis and has therefore been proposed as an early biomarker for detection of Alzheimer ́s disease." (PMID 37936126, 2023). "In addition to identifying novel individual genes, proceeding from our integrated Alzheimer’s disease mechanism network, we propose three disease initiating routes via extra-cellular ligands like CD4, DCN and IL8." (PMID 26784894, 2016). "Besides finding the microRNAs that could regulate the critical nodes such as APP, BACE1, CD4, DCN, IL8 and PSEN1, we searched to uncover additional regulatory mechanisms of Alzheimer’s disease genes." (PMID 26784894, 2016).
amyloid (3 papers, 2021 to 2024). "Unlike HSPG, which tends to be evenly distributed in neuritic plaques (NPs) containing amyloid, decorin is mainly distributed around spherical amyloid plaques and the edges of amyloid fiber bundles." (PMID 34512308, 2021). "We further confirmed the in vivo presence of these C3+ Decorin+ astrocytes and that these cells are associated with vascular amyloid but not with parenchymal amyloid deposits in mouse models and AD/CAA patients." (PMID 35351973, 2022). "Decorin+ astrocytes were rarely found in control tissue; however, we found that in all human AD/CAA patient brain samples analyzed, Decorin+ astrocytes were associated with vascular amyloid accumulation but not with parenchymal amyloid plaques." (PMID 35351973, 2022). "The role of DCN in amyloidosis pathogenesis remains unclear." (PMID 39288026, 2024). "Furthermore, these Decorin+C3+ astrocytes maintain their phagocytic capacity and exhibit a neurotoxic gain of function and are associated with vascular amyloid deposits but not parenchymal amyloid plaques in mouse models and AD/CAA patients." (PMID 35351973, 2022). "The lack of decorin in the center of certain amyloid plaques indicates that the distribution of DSPGs is spatially restricted." (PMID 34512308, 2021).
aortic aneurysm (3 papers, 2019 to 2022). A ruptured aneurysm located in the wall of the proximal portion of the descending aorta proceeding from the arch of the aorta. "In murine model of Aortic Aneurysms, systemic Serpina3n treatment was shown to reduce degradation of the proteoglycan decorin while increasing collagen density the aorta of mice, leading to a reduced frequency of aortic rupture and death." (PMID 36204224, 2022). "In murine models of aortic aneurysm, deficiency in GrB activity was found to reduce cleavage of ECM proteins decorin and fibrillin-1, increase microfibril structural integrity and improved collagen organization, leading to decreased aneurysm rupture and mortality." (PMID 36204224, 2022). "Decorin has been proposed to have multiple roles depending on where it is located within the aortic wall, which may influence the development of aortic aneurysms." (PMID 36012466, 2022).
Arthritis (3 papers, 2017 to 2023). Inflammation of a joint. "Decorin, a small molecule weight of PG, was able to induce both arthritis and fibrosis, so we used decorin that promoted MSC1 polarization to challenge murine and find if NBF of AS was a result of MSC2 polarization promoted by high level of IL-17A." (PMID 29228588, 2017).
bladder tumours (3 papers, 2013 to 2017). "Therefore, in bladder tumours, the loss of decorin expression eliminates IGF-IR activity and signaling repression, promoting cellular motility, invasion, and cancer progression." (PMID 29207682, 2017). "Altogether, our results show that decorin expression in human bladder tumours promotes progression of these tumours to an invasive stage." (PMID 24142880, 2013). "It has also been shown with IHC analysis, that decorin immunoreactivity is markedly reduced in the tumour stroma of both low and high grade bladder tumours." (PMID 24146840, 2013). "Interestingly, using our exon array data for bladder wall muscle, normal urothelium and bladder tumours, we observed that DCN was transcribed from at least two promoter regions in bladder tissues." (PMID 24142880, 2013). "To identify the physiological pathways that DCN could affect during bladder tumour progression, we identified genes with expression profiles correlated or anti-correlated with DCN within MIBC (Pearson correlation coefficient)." (PMID 24142880, 2013). "Our results demonstrate that decorin is required and sufficient to promote progression of the MB49 bladder tumour in vivo." (PMID 24142880, 2013). "Kdr and Cdh5 were also downregulated in mouse MB49-I tumours following decorin knockdown, thus suggesting involvement of DCN in regulation of angiogenesis during human bladder tumour progression." (PMID 24142880, 2013). "Nevertheless, other studies demonstrate a possible tumour suppressor role for decorin, where bladder tumour tissues are entirely devoid of decorin expression while non-malignant stromal areas express this proteoglycan." (PMID 29207682, 2017). "In several libraries of human bladder tumours, we observed that decorin was upregulated in muscle-invasive as compared to non-invasive bladder tumours." (PMID 24142880, 2013).
breast invasive ductal carcinoma (3 papers, 2010 to 2025). "Decorin mRNA was also lacking from the infiltrating cancer cells of the invasive ductal carcinoma (IDC) and the invasive lobular carcinoma (ILC) (data not shown)." (PMID 23007289, 2013).
coronary artery disease (3 papers, 2017 to 2025). "In patients with AS with and without ATTR-CM, levels of decorin and HGF correlated positively with age and the presence of coronary artery disease." (PMID 41141478, 2025).
esophageal squamous cell carcinoma (3 papers, 2015 to 2024). Esophageal squamous cell carcinoma (ESCC) is a type of esophageal carcinoma (EC) that can affect any part of the esophagus, but is usually located in the upper or middle third. "Compared to subjects with the lowest quartile of plasma decorin, those with the highest quartile had a significantly lower risk of having esophageal squamous cell carcinoma (ESCC)." (PMID 39600538, 2024). "Serum decorin levels have been recognized as a potential biomarker in patients with acute ischemic stroke or esophageal squamous cell carcinoma." (PMID 25781946, 2015). "Moreover, in esophageal squamous cell carcinoma in humans decreased plasma decorin concentrations (5.6 ± 3.6 ng/ml) were observed compared to control patients (7.8 ± 3.1 ng/ml)." (PMID 30022402, 2018).
Kaposi's sarcoma (3 papers, 2013 to 2017). A malignant neoplasm characterized by a vascular proliferation which usually contains blunt endothelial cells. "The inconsistency could be explained by the different methods to detect decorin expression, like the use of different antibodies, and by the analysis of different tumor tissues (e.g., Kaposi Sarcomas)." (PMID 24634138, 2014). "We have previously shown that decorin expression is lacking from Kaposi’s sarcoma and angiosarcoma." (PMID 28653173, 2017).
liver cirrhosis (3 papers, 2022 to 2025). "The altered ECM landscape in liver cirrhosis include the upregulation of collagens (type I, III, IV, V, VI, VIII, X, XI, XII, XIV, XV, XVI, XVIII, XXI), proteoglycans such as versican, decorin, lumican, and glycoproteins including fibulins, fibronectin, and laminins (Dataset EV5)." (PMID 35579278, 2022).
malignant glioma (3 papers, 2014 to 2017). A grade III or grade IV glioma arising from the central nervous system. "Particularly, the ectopic expression of decorin in human malignant glioma cells enhances the alloreactive immune response mediated by CD8+, CD4+ T cells, and NK cells." (PMID 26379028, 2015).
metastatic cancer (3 papers, 2019 to 2022). A carcinoma which has spread from the original site of growth to another anatomic site. "Several studies have addressed the role of decorin in human metastatic cancers, and results are contradictory." (PMID 32824864, 2020). "Furthermore, the post-transcriptional regulation of DCN is still questionable, although it is well accepted that it is an important mechanism of developing metastatic cancer." (PMID 35052821, 2022).
muscular dystrophy (3 papers, 2012 to 2023). Muscular dystrophy (MD) refers to a group of more than 30 genetic diseases characterized by progressive weakness and degeneration of the skeletal muscles that control movement. "Mice from both muscular dystrophy models were IP injected on alternate days for three weeks testing recombinant DCN proteins expressed together with both peptides: CAR and mCAR." (PMID 34575582, 2021). "This may indicate that although CAR peptide is able to target muscular dystrophy lesions thoroughly, the therapeutic protein in the fusion molecule, DCN, defines some of its localization within the targeted area." (PMID 34575582, 2021). "DCN binds to collagens and TGF-β, and its level has been found to correlate with increased fibrosis in different muscular dystrophies." (PMID 38130476, 2023).
myopia (3 papers, 2012 to 2021). "Extracellular matrix components such as collagen type I alpha 1 (COL1A1), collagen type II alpha 1 (COL2A1), lumican (LUM), decorin (DCN) and epiphycan (EPYC or DSPG3) have been previously assessed for genetic associations with myopia." (PMID 23077567, 2012).
myxoma (3 papers, 2017 to 2024). A benign soft tissue neoplasm characterized by the presence of spindle and stellate cells, lobulated growth pattern, and myxoid stroma formation. "The only difference found between intramuscular myxoma and grade I myxofibrosarcoma was in the expression of decorin, a matrix proteoglycan, which was expressed in myxofibrosarcomas but not in myxomas." (PMID 28160572, 2017). "Moreover, increased RNA and protein levels of collagen VI chain α1 and decorin in grade I myxofibrosarcoma relative to intramuscular myxoma were confirmed by real-time polymerase chain reaction and IHC, respectively." (PMID 34957097, 2021). "Compared with fibroblasts, myxoma cells downregulate the markers of fibroblasts such as COL1A1 and DCN but still retain some abilities of collagen secretion." (PMID 39090109, 2024). "In contrast to intramuscular myxoma, grade I myxofibrosarcoma uniquely expressed collagen XII chain α1 and collagen XIV chain α1, as well as five proteoglycans (lumican, proteoglycan 4, prolargin, decorin and biglycan)." (PMID 34957097, 2021).
osteogenesis imperfecta (3 papers, 2016 to 2023). Osteogenesis imperfecta (OI) comprises a heterogeneous group of genetic disorders characterized by increased bone fragility, low bone mass, and susceptibility to bone fractures with variable severity. "The changes in collagen fibrils in an osteogenesis imperfecta model and the double gene deletion of decorin and biglycan were structural because these proteins were involved in either the conformational changes of the collagen subunit or the knitting of collagen fibrils." (PMID 31988398, 2020). "The absence of decorin increases the severity of osteogenesis imperfecta." (PMID 36981001, 2023).
Peritoneal Fibrosis (3 papers, 2015 to 2025). Disorder characterized by a wide range of structural changes in PERITONEUM, resulting from fibrogenic or inflammatory processes. "Furthermore, the reported association between low decorin levels and more extensive peritoneal fibrosis in patients undergoing PD further strengthens the role of decorin as an anti-fibrotic agent and a potential therapeutic target in this population." (PMID 40283096, 2025). "Intraperitoneal administration of plasmid DNA expressing decorin with gold nanoparticles inhibited peritoneal fibrosis by inhibiting the effects of TGF-β1 in a rat peritoneal fibrosis model." (PMID 30410706, 2017). "This study shows that both gold nanoparticles and adenoassociated virus mediated decorin gene therapies significantly decrease peritoneal fibrosis in vivo in a rodent model." (PMID 26236720, 2015). "Intraperitoneal administration of AAVs expressing decorin significantly inhibited peritoneal fibrosis, associated with preserved peritoneal cell size, decreased peritoneal thickness, and decreased expression of α-SMA in the peritoneum in a mouse peritoneal fibrosis model." (PMID 30410706, 2017). "Another study reported that intraperitoneal administration of adenoviral vectors expressing decorin, which blocks TGF-β1 signaling, inhibited collagen accumulation in the peritoneum but failed to improve the ultrafiltration rate of the peritoneal membrane in a rat peritoneal fibrosis model." (PMID 30410706, 2017).
rheumatoid arthritis (3 papers, 2020 to 2022). A chronic, systemic autoimmune disorder characterized by inflammation in the synovial membranes and articular surfaces. "High levels of soluble forms of BGN and DCN were found in synovial fluid of OA or rheumatoid arthritis patients." (PMID 32466468, 2020). "Extensive degradation of both large and small PGs, such as decorin and biglycan were found in cartilages of patients suffering from OA and rheumatoid arthritis (RA)." (PMID 32353084, 2020).
adenoma (2 papers, 2018 to 2020). A neoplasm arising from the epithelium. "Immunohistochemistry of DCN showed mild positive reaction in epithelial cells and in the stroma in adenoma." (PMID 33322258, 2020). "The other two genes, DCN and SPP1, were down-regulated in adenoma, AEM and AEC, and up-regulated in advanced carcinoma." (PMID 33322258, 2020). "The aim of this study was to determine whether the expression of selected ECM-related genes (DCN, EPHA4, FN1, SPARC, SPON2, and SPP1) was similar in adenoma and AEM but differed from the expression in AEC and advanced carcinoma." (PMID 33322258, 2020). "Although upregulated when compared carcinoma to adenoma, the overall expression of DCN is downregulated when carcinoma to normal and adenoma to normal is compared." (PMID 30175151, 2018).
autoimmune disease (2 papers, 2021 to 2022). A disorder resulting from loss of function or tissue destruction of an organ or multiple organs, arising from humoral or cellular immune responses of the individual to their own tissue constituents. "This review article summarizes the characteristics of decorin in immune and inflammatory diseases and discusses the potential role of decorin in autoimmune diseases." (PMID 36033387, 2022).
B cell chronic lymphocytic leukaemia (2 papers, 2020 to 2026). "Production of DCN in B cells has been demonstrated in the setting of early stage B cell chronic lymphocytic leukaemia and further clinical and preclinical studies are needed to elucidate their functional and prognostic significance in solid tumours." (PMID 41392017, 2026). "Indeed, transcriptional analysis of tumor progression at the mRNA level revealed high decorin expression during the early stages of tumorigenesis in B-cell chronic lymphoid leukemia (CLL), in contrast to its suppression in advanced stages." (PMID 32477937, 2020).
benign hemangiomas (2 papers, 2013 to 2020). "Similarly, while benign hemangiomas displayed relatively high decorin mRNA levels, the transcription of decorin was completely blocked in malignant vascular sarcomas." (PMID 32477937, 2020).
brain tumor (2 papers, 2014 to 2015). "Decorin inhibits cell proliferation in several tumor cell types, including ovarian, liver, and brain tumor cells." (PMID 26248280, 2015). "In addition, AAV-mediated decorin gene delivery warrants further investigation as a potential therapeutic approach for brain tumors." (PMID 24625664, 2014).
cataract (2 papers, 2021). Partial or complete opacity of the crystalline lens of one or both eyes that decreases visual acuity and eventually results in blindness. "Considering the proximity of the aqueous humor to the crystalline lens, cataract severity may be associated with changes in decorin concentrations." (PMID 34947953, 2021). "We examined whether the expression levels of DCN were associated with human cataracts and aging." (PMID 33918979, 2021). "It will be interesting to study the relationship between decorin concentrations and severity of cataracts in future studies." (PMID 34947953, 2021).
cerebral amyloid angiopathy (2 papers, 2022 to 2026). "Building upon our previous findings, we demonstrate that lead exposure may induce cerebral amyloid angiopathy (CAA) pathology through the formation of C3+ decorin+ A1-like astrocytes mediated by endothelial cell PAI-1." (PMID 41744606, 2026).
chronic kidney disease (2 papers, 2015 to 2023). Impairment of the renal function secondary to chronic kidney damage persisting for three or more months. "Decorin seems to be increased in processes of kidney fibrosis and development of chronic kidney disease." (PMID 37250906, 2023).
colon adenocarcinoma (2 papers, 2017 to 2020). "Another report showed a dramatic increase of decorin and versican in colon adenocarcinoma, which constitute the vast majority of the CS/DS-proteoglycans, and a deep altered chain composition and length." (PMID 28827814, 2017).
colorectal tumor (2 papers, 2020 to 2024). "In line with that, oncolytic adenovirus-mediated decorin and GM-CSF gene transfer inhibited tumor growth in a colorectal tumor model." (PMID 32824864, 2020).